DIO1 (iodothyronine deiodinase 1)
Diseases named in the same sentence as DIO1 in open-access papers (continued):
Sharing a sentence is not in itself a finding about the gene and the disease.
Sepsis (2 papers, 2017 to 2021). Sepsis is defined as life-threatening organ dysfunction caused by a dysregulated host response to infection. "Experimental sepsis in mice resulted in reduced T4 serum levels and liver Dio1 (Type I iodothyronine deiodinase) expression, hallmarks of NTIS." (PMID 34945151, 2021). "Herein, we aimed to evaluate the central and peripheral expression of genes involved in the transport (MCT8/Slc16a2 and MCT10/Slc16a10), metabolism (Dio1, Dio2, and Dio3) and action (Thra and Thrb) of TH during NTIS induced by fasting or sepsis." (PMID 29118715, 2017). "In CLP-induced sepsis group, Dio1 expression was decreased by 49% (P < 0.05) and Dio3 expression did not change between CLP-induced sepsis and Sham groups." (PMID 29118715, 2017).
thyrotoxicosis (2 papers, 2021 to 2022). A hypermetabolic syndrome caused by the elevation of thyroid hormone levels in the serum. "The expression of T3-regulated genes, including Hr, Dio1, Gpd2, Dbp, and Klf9, was markedly elevated in Dio3–/– fetuses compared with Dio3+/+ littermates, indicating thyrotoxicosis in all tissues." (PMID 36166296, 2022). "It was first reasoned that, due to reduced cerebral T3 uptake, a progressive buildup of T3 in serum stimulates DIO1 activity in peripheral tissues, thus further aggravating the peripheral thyrotoxicosis by enhancing T4 to T3 conversion." (PMID 34539576, 2021). "Following these observations, it was hypothesized that by combining T4 with propylthiouracil (PTU), which inhibits DIO1 in peripheral tissues, the aggravation of the thyrotoxicosis could be overcome." (PMID 34539576, 2021).
type 2 diabetes (2 papers, 2018 to 2022). "Similarly, in the streptozotocin (STZ)-induced type 2 diabetes rat model, Dio1 activity and mRNA expression level in rats recoved to control levels after administration of T3 treatment and increased significantly when T3 and insulin were co-administrated." (PMID 36605939, 2022).
autoimmune type 1 diabetes (1 paper, 2018). Autoimmune disease wherein the body's own immune system attacks and destroys the cells within the pancreas that produce insulin. "NOD mice, which are a polygenic model for autoimmune type 1 diabetes, had lower expression of Dio1 and Txnrd1 relative to other strains; Se deficiency, however, resulted in increased expression of Dio1 and Txnrd1 relative to the other strains in NOD mice." (PMID 29338053, 2018).
bipolar disorder (1 paper, 2024). A disorder of the brain that causes unusual shifts in mood, energy, activity levels and the ability to carry out day-to-day tasks. "Noteworthy findings include associations of DRD3 with IL6 and TP35 in chronic alcoholic intoxication, alongside implications of DIO1 (a selenium target), DIO2, and DRD3 in thyroid diseases and bipolar disorders, hinting at potential connections to pathways involving exercise and ROS." (PMID 39635461, 2024).
cardiac hypertrophy (1 paper, 2020). "To exclude a global effect of PTU on Dio2 as well as on Dio1 activity, we assessed TAC-induced cardiac hypertrophy in 8- to 10-week-old cKO, control littermates (WT), and age-matched αMHC-Cre-expressing control mice (herein termed Cre)." (PMID 32439985, 2020).
glioblastoma (1 paper, 2023). The most malignant astrocytic tumor (WHO grade IV). "Other SNPs in the DIO1 gene, associated with control of thyroid hormone metabolism, were found to have a significant prognostic value in adult glioblastoma patients." (PMID 37878192, 2023).
Graves' hyperthyroidism (1 paper, 2023). "The genes related to the antithyroid effects of long-term iodine loading are Slc5a5, Slc26a4, Duox2, and Duoxa2, in addition to Tpo, Dio1, and Slco4a1, which are upregulated in Graves' hyperthyroidism." (PMID 36565031, 2023).
gynecologic cancer (1 paper, 2024). "Although DIO1 action is reported to be disturbed in several malignancies, no work has been conducted in high‐grade serous ovarian carcinoma (HGSOC), the most lethal gynecologic cancer." (PMID 38429887, 2024).
Insulin resistance (1 paper, 2025). Increased resistance towards insulin, that is, diminished effectiveness of insulin in reducing blood glucose levels. "During prediabetes, the conversion of FT4 to FT3 is impaired due to decreased activity of type 1 deiodinase (DIO1) and type 2 deiodinase (DIO2), and this can be attributed to the oxidative stress associated with insulin resistance." (PMID 40076791, 2025).
liver cirrhosis (1 paper, 2023). "Hence, in liver cirrhosis, a reduced DIO1 capacity in the liver (and perhaps depleted glutathione levels), might be additional mechanisms to systemic inflammation of NTIS in AD and ACLF, which may explain the relatively early occurrence of NTIS before patients enter a critically ill state." (PMID 36755907, 2023).
lung adenocarcinoma (1 paper, 2020). A carcinoma that arises from the lung and is characterized by the presence of malignant glandular epithelial cells. "High expression of DIO1 indicated a good prognosis in Lung Adenocarcinoma (LUAD)." (PMID 32316597, 2020).
ovarian carcinoma (1 paper, 2024). A malignant neoplasm originating from the surface ovarian epithelium. "In this study, we have identified a unique expression pattern of DIO1 in ovarian cancer cells and tissues and provided evidence, by several complementary methods, suggesting that this enzyme has tumor‐suppressive activities." (PMID 38429887, 2024). "These global changes in protein expressions upon DIO1 silencing provide mechanistic explanation for the proliferative phenotype in ovarian cancer cells." (PMID 38429887, 2024). "Our studies indicated that DIO1 induction in ovarian cancer cells attenuates proliferation and tumor growth." (PMID 38429887, 2024). "Silencing or inhibiting the enzyme led to enhanced ovarian cancer proliferation, while an opposite effect was shown following DIO1 ectopic expression." (PMID 38429887, 2024). "To better comprehend the global effects of DIO1 expression and the cell phenotype in ovarian cancer following DIO1 silencing, we performed proteomic analysis." (PMID 38429887, 2024). "In conclusion, DIO1 expression and ovarian cancer progression are inversely correlated, highlighting a tumor suppressive role for this enzyme and its potential use as a biomarker in this disease." (PMID 38429887, 2024). "After observing that DIO1 acts to attenuate ovarian cancer cell proliferation, together with its decreased expression in HGSOC compared to normal cells, we examined the outcome of lowering this protein by direct catalytic inhibition or silencing the DIO1 enzyme." (PMID 38429887, 2024). "In summary, we demonstrate the first indication in ovarian cancer that DIO1 is an anti‐tumor factor in the carcinogenic process, suggesting that reduction in its expression, consistently observed in several HGSOC cell lines and human tissues, may promote tumorigenesis in this aggressive disease." (PMID 38429887, 2024). "The basal levels of DIO1 were analyzed in HGSOC cells (ES‐2 and Kuramochi), which were shown to correlate with the genomic profiling of ovarian cancer patients." (PMID 38429887, 2024). "Flow cytometry (FC) analysis, using AF‐647‐tagged DIO1 antibody, indicated that the ovarian cancer cells express lower DIO1 protein levels compared to the normal cell models." (PMID 38429887, 2024).
pituitary tumor (1 paper, 2020). A benign or malignant neoplasm affecting the pituitary gland. "SRSF1 participates in the pituitary tumor machinery regulating the isoforms generated from the DIO1 gene." (PMID 33261069, 2020).
preeclampsia (1 paper, 2021). Preeclampsia is a hypertensive disorder of pregnancy that is characterized by new-onset hypertension with proteinuria presenting after 20 weeks of gestation, and depending on mild or severe forms may initially present with severe headache, visual disturbances, and hyperreflexia. "According to this, to fully investigate how preeclampsia disturbed thyroid function at the metabolic level, we detected the hepatic Dio1." (PMID 34195279, 2021).
prostate carcinoma (1 paper, 2020). A carcinoma that arises from epithelial cells of the prostate gland. "We also observed higher levels of DIO1, DIO2, and SELENOS, and lower levels of SELENOI in all the prostate cancer cell lines." (PMID 32933107, 2020).
renal tumors (1 paper, 2017). "To check if genes affected by DIO1 expression could be linked with altered DIO1 function in renal tumors, we analyzed their expressions in tissue samples derived from 30 patients with ccRCC." (PMID 29272308, 2017). "As previously reported, the expression of DIO1 transcript was markedly decreased in renal tumors." (PMID 29272308, 2017).
serous ovarian carcinoma (1 paper, 2024). "The selenoenzyme deiodinase type 1 (DIO1) has anti‐tumor actions in high‐grade serous ovarian cancer." (PMID 38429887, 2024). "DIO1 diminished expression in high‐grade serous ovarian cancer, both in vitro and in human tissues, together with indications that high RNA expression positively correlates with patient's survival, led us to hypothesize that the enzyme may function as a tumor suppressor." (PMID 38429887, 2024).
steatosis (1 paper, 2021). Increased lipid within the cytoplasm of cells. "Of these genes, 11 coded for selenoproteins of which four genes had lower expression (SELENON, SELENOO, GPX1, and TXNRD3) and seven genes had higher expression (SELENOK, SELENOS, SELENOW, GPX2, GXP3, DIO1, and SEPHS2) in steatosis." (PMID 34869521, 2021). "Four genes had lower expression in steatosis (ABCA1, MTR, MTHFR, and PLG) and five genes had higher expression (SEPHS2, DIO1, HBB, SAA1, and SAA2) in the “selenoprotein micronutrient network” pathway." (PMID 34869521, 2021). "Amongst the selenoproteins associated with the metabolism of cholesterol, our findings revealed a higher expression of DIO1 in the disease groups (NASH and steatosis) when compared to healthy obese controls." (PMID 34869521, 2021). "Amongst the 13 genes, eight (DIO1, GPX2, SEPHS2, SELENOK, SELENOS, SELENOT, SELENOF, and SELENOW) had higher, and five (DIO3, GPX1, SELENON, SELENOO, and TXNRD3) had lower expression in steatosis." (PMID 34869521, 2021). "Besides the selenoproteins GPX2, DIO1, and SEPHS2, the gene for TRNAU1AP also had higher expression in steatosis in the “selenium metabolism and selenoproteins” pathway, and TXNRD3 had lower expression in steatosis." (PMID 34869521, 2021).
tumor (10 papers, 2011 to 2024). "Based on the expanded correlation analysis results, we found that ACOX1, ALDH2, FUT6, and LRRC19 have a high association with GPX3 and DIO1 in the TCGA database, whether it is only tumor samples or “tumor samples + normal samples”." (PMID 32316597, 2020). "Lastly, we wanted to establish, by an additional approach, that DIO1 inhibition contributes to tumor progression." (PMID 38429887, 2024). "Strikingly, and counterintuitively to the anti-tumor activity of DIO1, restoration of DIO1 expression resulted in moderate increase of TKT, NAMPT and IDH2 protein levels." (PMID 29272308, 2017). "In the present study we observed nearly 3-fold reduction of DIO1 mRNA expression while DIO1 protein was lost in tumor samples." (PMID 21912701, 2011). "SQ-PCR analysis revealed 2.7 fold downregulation of DIO1 mRNA in 32 paired tumor and control tissue samples (p = 0.0009), which is consistent with our previous reports." (PMID 21912701, 2011). "The molecular mechanisms responsible for the tumor promoting phenotype following DIO1 silencing were elucidated by changes in signaling pathways regulating cell proliferation, including a significant elevation in pERK and a reduction in the cell cycle inhibitor p21." (PMID 38429887, 2024). "Results indicate that DIO1 expression varied between patients, with four cases exhibiting negative staining, four low staining, and two presenting moderate expression in scattered tumor regions." (PMID 38429887, 2024). "We also analyzed the expression of GPX3 and DIO1 with the KIRC tumor stage." (PMID 32316597, 2020). "It would be interesting to see if changes in DIO1 expression may affect other cells and processes that contribute to tumor formation, in particular angiogenesis or infiltrating cells of immune system." (PMID 29272308, 2017). "This has been supported by the negative correlation between tumor-specific changes in miR-224 and DIO1 mRNA levels and loss of DIO1 protein in ccRCC samples." (PMID 21912701, 2011). "Moreover, tumor-specific changes in concentration of product of DIO1 activity, T3, correlate negatively with changes of miR-224 expression." (PMID 21912701, 2011). "To check whether miR-224-mediated downregulation of DIO1 affects DIO1 activity product, T3, we analyzed the correlation between tumor-specific changes of miR-224 and T3 levels." (PMID 21912701, 2011). "Moreover, Dio1 activity has been altered in some tumor types." (PMID 34445217, 2021). "Although these changes between the respective tumor differentiation grades are not statistically significant they may possibly suggest that as tumor progress the impact of miR-224 on DIO1 expression lowers and perhaps other posttranscriptional mechanisms are involved." (PMID 21912701, 2011). "We studied DIO1 expression in HGSOC patients [The Cancer Genome Atlas (TCGA) data and tumor tissues], human cell lines (ES‐2 and Kuramochi), normal Chinese hamster ovarian cells (CHO‐K1), and normal human fallopian tube cells (FT282 and FT109)." (PMID 38429887, 2024). "The results showed that the expression of IPCEF1, TFF3, GLT8D2, TPO and DIO1 were downregulated in the tumor group and DPP4, LRP4, CDH3, KCNJ2, CLDN1, GABRB2, FN1 were upregulated in the tumor group." (PMID 39513122, 2024). "The transcription levels of GPX3 and DIO1 were significantly lower in KIRC patients than normal control cases in subgroup analysis based on gender, age, tumor grade, and nodal metastasis status." (PMID 32316597, 2020). "Similarly, Iodothyronine Deiodinase 1 (DIO1), a gene involved in the activation and inactivation of thyroid hormone whose low expression is said to promote tumor progression was also upregulated in patients with positive margins." (PMID 38038766, 2024). "Statistically significant negative correlation was observed between miR-224 and DIO1 mRNA tumor-specific changes of expression (Spearman rs = −0.556 at p = 0.001)." (PMID 21912701, 2011).
tumor (continued). "To explore whether GPX3, DIO1, and LRRC19 still correlate when including the normal tissue samples, we performed correlation analysis in the datasets of “523 TCGA tumor cases + 72 TCGA normal cases” and “523 TCGA tumor cases + 72 TCGA normal cases + 28 GTEx Kidney-Cortex cases”." (PMID 32316597, 2020).
cancer (8 papers, 2006 to 2025). A tumor composed of atypical neoplastic, often pleomorphic cells that invade other tissues. "At the same time, the results of our study may possibly suggest that loss of DIO1 expression in ccRCC tumors could be an adaptive mechanism, protecting the cells against overstimulation of cancer metabolism and induction of autophagy and or apoptosis." (PMID 29272308, 2017). "We further observed under DIO1 depletion upregulation in an array of proteins involved mainly in cancer cell proliferation." (PMID 38429887, 2024). "Dot plots described the differential gene expression levels with respect to GPX3 and DIO1 among the 33 TCGA cancer types." (PMID 32316597, 2020). "Survival maps, i.e. heat maps of hazard ratio (HR), showed the prognostic value of GPX3 and DIO1 in pan-cancer." (PMID 32316597, 2020). "In summary, the results of this and our previous study suggest that restoration of DIO1 expression affects functioning of cancer cells in two modes." (PMID 29272308, 2017). "This collective evidence proposes that DIO1 reduction in cancer may be a common phenotype, implying a mechanistic role." (PMID 38429887, 2024). "As our mechanistic data suggests, GPx4 significantly contributes to HCC protection by selenium, even if other selenoproteins as SELP, DIO1 and TXNRD2 show similar positive association with cancer survival and may also be involved." (PMID 29515790, 2018). "This first study addressing effects of deiodinase re-expression on proteome of cancer cells demonstrates that induced DIO1 re-expression in renal cancer robustly downregulates oncoproteins, affects key metabolic pathways, and triggers proteins involved in anti-oxidative protection." (PMID 29272308, 2017). "Remarkably, although the regulation of DIO1 expression is relatively well understood, the global effects of DIO1 expression in cancer remain unknown." (PMID 29272308, 2017). "These aspects of DIO1 activity in cancer cells should be investigated in the future." (PMID 29272308, 2017). "However, the global effects of DIO1 expression in various tissues affected by cancer remain unknown." (PMID 29272308, 2017). "Moreover, gene expression profiling in normal versus malignant thyroid tissues demonstrated a downregulation of DIO1 and DIO2, which could be linked to Pax8 loss during cancer progression." (PMID 22531031, 2012). "In accordance with our recent study, DIO1 expression resulted also in suppression of TGFBI, and several other proteins (e.g. PODXL, CD74) that promote RCC progression or act as oncogenic proteins in other cancers (e.g. FMNL2, APBB1IP, ASAP1, and LRRFIP1)." (PMID 29272308, 2017). "Notably, TPO, DIO1, and SLC26A4 were consistently downregulated in both cancer subtypes." (PMID 40746809, 2025). "In addition, for the four types of cancer, only one of GPX3 or DIO1 showed prognostic value." (PMID 32316597, 2020).
DIO1 also shares sentences with these, for which no sentence is quoted: Anxiety (1 paper); autoimmune thyroiditis (1); congenital hypothyroidism (1); degenerative diseases (1); endocrine system disorder (1); fibrosis (1); hypercholesterolaemia (1); inflammation (1); kidney cancer (1); kidney neoplasia (1); lung carcinoma (1); mood disorder (1); nutritional disorder (1); prediabetes (1); protein-energy malnutrition (1); rectal cancer (1); renal cell carcinoma (1); Stroke (1); Thyroid adenoma (1); thyroid tumor (1); Zinc deficiency (1).